SEMA6D (semaphorin 6D)
Diseases named in the same sentence as SEMA6D in open-access papers (continued):
Sharing a sentence is not in itself a finding about the gene and the disease.
tumor (continued). "Tumor progression was significantly suppressed in Sema6d-KO mice compared with WT mice." (PMID 38329122, 2024). "However, the precise role of SEMA6D in macrophage polarization within the tumor microenvironment remains incompletely elucidated." (PMID 38067240, 2023). "Here, we show that semaphorin 6D (Sema6D) forward signaling, which is reportedly involved in coordinating the orientation of cell development and migration as a guidance factor, impaired the infiltration and activation of tumor-specific CD8+ T cells in murine oral tumors." (PMID 38329122, 2024). "Of these seven, six genes—ECT2, NCEH1, TNFSF10, FNDC3B, GHSR, and SEMA6D—have either been observed at elevated expressions in tumor cells or have been documented acting as oncogenes for specific cancers in humans (genes that can transform cells into tumor cells)." (PMID 33767816, 2021). "In sum, our model uniquely integrates SEMA6D-mediated immune evasion and CXCL9-driven anti-tumor immunity, offering a bi-directional molecular framework to refine risk stratification and boost ICI efficacy." (PMID 41438751, 2025). "SEMA6D overexpressioninduced proliferation in the normal breast cell line, MCF10A, hintingat a tumor-initiating role." (PMID 35571788, 2022). "Researchers found that SEMA6D is predominantly expressed by non-hematopoietic cells, especially tumor cells, and shows a strong negative correlation with CD8A, PDCD1, IFNG and GZMB." (PMID 41438751, 2025). "While this treatment did not alter tumor progression in WT mice, it significantly reduced tumor weight in Sema6d-KO mice." (PMID 38329122, 2024). "To confirm whether CD8+ T cells are responsible for inhibiting tumor progression and enhancing activation of the antitumor immune response in Sema6d-KO mice, we performed MOC2 transplantation with or without anti-CD8 antibody treatment to deplete CD8+ T cells." (PMID 38329122, 2024). "Similarly, hsa-miR-23a-3p seems to enhance tumor and vascular growth in CRC via the Signal Transducer and Activator of Transcription 3/miR-23a-3p/Semaphorin 6D (STAT3/miR-23a-3p/SEMA6D) axis induced by Interleukin-17C (IL-17C), which also leads to VEGF production." (PMID 37444431, 2023). "However, transplantation of these Sema6d-expressing cell lines into Sema6d-KO mice could induce an immune reaction to Sema6D as a non-self antigen, leading to tumor shrinkage." (PMID 38329122, 2024). "Since Sema6D derived from nonhematopoietic cells seemed to regulate CD8+ T cell function in the TME, we investigated the role of Plexin-A1 and Plexin-A4, which are receptors for Sema6D, in T cells isolated from tumor-draining LNs." (PMID 38329122, 2024). "Tumor growth, the number of tumor-infiltrating CD8+ T cells, and the subsets of CD8+ T cells were comparable between mice that received WT T cells and those that received Sema6D-KO T cells, suggesting that Sema6D expressed by T cells is not involved in the immunosuppressive mechanism." (PMID 38329122, 2024).
cancer (16 papers, 2014 to 2025). A tumor composed of atypical neoplastic, often pleomorphic cells that invade other tissues. "Some studies have confirmed that semaphorin 6D (Sema6D) is associated with the proliferation and migration of various cancer cells, vascular regeneration, immune metabolism, and neural regeneration." (PMID 40777970, 2024). "In other words, according to in vitro studies and clinical observation, deficiency of SEMA6B (described earlier) and SEMA6D expression are found in breast tumors and coincide with cancer growth, chemoresistance, and recurrence." (PMID 38067240, 2023). "Although SEMA6D was implicated in migration inthe context of developmentand cancer, its role in EMT, which is related to the migratory phenotype,has not been investigated thoroughly." (PMID 35571788, 2022). "Therefore, future research using conditional knockout mice should investigate the role of Sema6d expressed by cancer-associated fibroblasts and endothelial cells." (PMID 38329122, 2024). "Among the members of the SEMA6 family, SEMA6B and SEMA6D have been implicated in cancer formation." (PMID 35269749, 2022). "The importance of Sema6d expressed by cancer cells was demonstrated using Sema6d-overexpressing MOC2OVA cells, which do not express endogenous Sema6d, and KPOVA cells, which naturally express Sema6d." (PMID 38329122, 2024). "Although several reports have examined the role of Sema6D in cancer, most evaluated the endogenous function of Sema6D in cancer cells." (PMID 38329122, 2024). "However, by contrast, SEMA6D overexpression is associated with resistance to cisplatin in osteosarcoma (OS) cells, which is regulated by miR-506, demonstrating that these effects may be specific to cancer types or to chemotherapy agents." (PMID 37685898, 2023). "Collectively, the presented reports indicate a possible modulatory role of SEMA6D in restricting the proliferation rate and chemoresistance of cancer breast cells." (PMID 38067240, 2023). "Overall, these data showed that SEMA6D overexpression has variableeffects in different cell lines that it induces proliferation in nontumorigenicMCF10A cells while reducing it in MCF7 cancer cells and showed noeffect on MDA MB 231 cancer cells." (PMID 35571788, 2022). "Dysregulation of semaphorins, a family of 20 related genes, is well established in cancer, and they are emerging as biomarkers and therapeutic targets, but relatively little is known specifically about SEMA6D in cancer." (PMID 34885090, 2021). "SEMA6D is a semaphorin related to immune responses, heart development, organogenesis, developmental angiogenesis, and cancer." (PMID 32492770, 2020). "Other cancer causing candidates were SMURF2, PIK3AP1, RSBN1, TTN and SEMA6D, which were ranked in the top 25% potential drivers in transposon insertional mutagenesis studies in mice." (PMID 29854292, 2018). "Within our data, we found expression of SEMA6D (semaphorin 6D) by cancer cells, a ligand of TREM2 involved in axon guidance, suggesting that cancer cells may serve as a source of instigating ligands in this signaling pathway." (PMID 39811671, 2025). "However, as for involvement in cancers, sema6D seems to exert the opposite impact regarding different types of cancers." (PMID 39061999, 2024). "SEMA6D expression negatively correlates with that of genes related to cytotoxic T cells and their activation in a public transcriptome data set of patients with cancer." (PMID 38329122, 2024). "Interestingly, ITIH5 and SEMA6D were reported as contributors to cancer cell metastasis." (PMID 34921655, 2022). "As an orthotopic cancer model, we transplanted MOC2 into the oral mucosa in WT and Sema6d-KO mice and observed their clinical course." (PMID 38329122, 2024). "Regarding other putative targets, such as SEMA6D, RGS2 and ANGPTL1, their involvement and modulation in cancer has been demonstrated but their interaction with miR-182 have yet to be explored." (PMID 25115394, 2014).
cancer (continued). "SEMA6D was mainly expressed in the TME by nonhematopoietic cells such as cancer cells, fibroblasts, and endothelial cells, and in normal mucosa it was also expressed by fibroblasts and endothelial cells." (PMID 38329122, 2024). "Thus, Sema6D forward signaling might be a vital biomarker for ICI resistance and a promising therapeutic target in a broad range of cancer types, including HNSCC, to improve ICI efficacy by inducing CD8+ T cell infiltration into tumors." (PMID 38329122, 2024).
SEMA6D also shares sentences with these, for which no sentence is quoted: autism spectrum disorder (1 paper); bladder tumor (1); cervical cancer (1); head and neck cancer (1); head and neck squamous cell carcinoma (1); infection (1); melanoma (1); multiple sclerosis (1); non-small cell lung carcinoma (1); osteoma (1); rheumatoid arthritis (1); scoliosis (1); Stroke (1).